CXCR3 (C-X-C motif chemokine receptor 3)
Diseases named in the same sentence as CXCR3 in open-access papers (continued):
Sharing a sentence is not in itself a finding about the gene and the disease.
tumor (continued). "In addition, the immunoregulatory effect of CXCL9, CXCL10, and the CXCL11/CXCR3 axis on tumor sites to promote antitumor immunity has been used as a new tumor therapeutic target." (PMID 35754838, 2022). "In CD8 T cells, the transcription factor HIF1α acts as a negative regulator of multiple chemokine receptors including CXCR3, which might suggest that tumour hypoxia could affect the tumour infiltration of cytotoxic lymphocytes." (PMID 34090499, 2021). "Future studies will address whether CXCR3 expression on tumor cells results in a more tumorigenic TME in the context of CXCL9 or CXCL10 secretion." (PMID 34433873, 2021). "Additionally, a significant increase in CXCR3+ T cells was also seen in the draining lymph nodes, suggesting their readiness to migrate to the tumor." (PMID 34336705, 2021). "The selective recruitment of CXCR3(+) B cells bridges the pro-inflammatory interleukin 17 response and the polarization of tumorigenic macrophages in the tumor environment, blocking the migration or function of CXCR3(+) B cells may help defeat HCC." (PMID 34235074, 2021). "Indeed, the majority of human PDAC tumors contain a subset of tumor cells expressing CXCR3 and exposure to CXCL10 induced resistance to gemcitabine." (PMID 34203869, 2021). "Currently, the precise role of CXCR3 in a specific type of tumor remains in debate." (PMID 33407095, 2021). "Additionally, CRISPR-Cas9 gene deletion studies showed that CXCR3 was critical for the trafficking of both tumor antigen-specific and bystander memory T cells to solid tumors." (PMID 34867942, 2021). "In light of these observations, it is possible that the CXCR3 KO donor TILs stemmed from the minority population that did not successfully ablate CXCR3 expression, but downregulated CXCR3 expression after reaching the tumor sites." (PMID 34867942, 2021). "Loss of CXCR3 or its ligands, CXCL9 or CXCL10, has been shown to disrupt the migration of adoptively transferred T cells to solid tumors resulting in impaired anti-tumor responses." (PMID 34867942, 2021). "To determine whether the neutralisation of IFN-γ might impact upon the CXCR3-CXCL9/10/11 chemokine axis, we examined the abundance of CXCR3+ T cell subsets in tumours and iLN." (PMID 33925140, 2021). "Therefore, this implies that CXCR3 expression is critical for tumor patients as an immunotherapeutic prognosis marker." (PMID 34680466, 2021). "It was shown that CXCL9, which is the ligand with the lowest affinity for CXCR3, has the function of regulating immune cell migration, differentiation, and activation, with contribution to tumor suppression, which accounts for the suppression of CXCL9/CXCR3 on GC." (PMID 33763365, 2021). "This hypothesis is further supported by the increased expression of CXCR3 in BRCA tumors compared to adjacent normal tissue, indicating CXCR3 is involved in a tumor specific immune response." (PMID 34440489, 2021). "In addition, higher frequency of CXCR3+ regulatory T cells in ovarian tumors can inhibit effector T responses to promote tumor progression." (PMID 33407095, 2021). "Results from our in vivo studies thus far have shown that GSK126 in combination with anti-PD-1, promotes the infiltration of activated T cells within the tumor perhaps trafficking from the draining lymph nodes where there is evidence of accumulation of CXCR3+ T cells." (PMID 34336705, 2021). "In addition, we observed increased numbers of CXCR3+ CD3+ T cells within the tumor, suggesting a possible CD20-TCB-dependent recruitment of peripheral activated and memory T cells, in line with previous observation using TCR mediated T cell activation." (PMID 33406104, 2021). "Revisiting CD8+ Tex CCR5 and CXCR3 progenitor/progeny expression patterns in the Clone 13 and preclinical tumor models may clarify this." (PMID 34354714, 2021).
tumor (continued). "Moreover, CXCR3, the receptor for CXCL10, is found to show over-expression within many malignant tumors, which has tumor growth-promoting activity and is associated with dismal survival and metastasis of many cancers 29,62-64." (PMID 34345201, 2021). "While the chemokine receptor CXCR3 has been shown to be critical for tumor-specific T cell migration to solid tumors, it is unknown whether the trafficking of bystander memory T cells to the tumors in absence of cognate Ag is also dependent on CXCR3." (PMID 34867942, 2021). "Thus, CXCR3 cognate chemokines can affect the recruitment of CTLs into the tumour mass and these effector cells can shape tumour immunity and anti-tumour therapy responses by antigen-specific or antigen-independent mechanisms." (PMID 33809369, 2021). "A small subset of BC cells specifically expressing CXCR3 exhibited tumor-initiating ability when cotransplanted with fibroblasts, driving JNK signaling, increasing expression of IL-1α/β, forming a supportive metastatic niche, and promoting lung metastatic tumor growth." (PMID 34602858, 2021). "Moreover, we identified the IFNγ-CXCL10 axis as being one of the drivers of TCB-mediated T cell infiltration in tumors, whereby IFNγ released by activated T cells induces CXCL10 secretion, which in turns attracts CXCR3-expressing T cells into the tumor sites." (PMID 33406104, 2021). "The loss of CXCR3 expression has been observed in multiple solid tumor types and is likely attributed to cell-extrinsic variables within the TME such as inhibitory receptor signaling and TGF-β secreted by tumor cells." (PMID 34867942, 2021). "When T cells derived from vaccinated mice were co-cultured with irradiated TC-1 tumor cells, the population of CXCR3+CD8+ T cells was higher than that when co-cultured with non-irradiated TC-1 cells, or when non-vaccinated T cells were co-cultured with irradiated TC-1 cells." (PMID 33469123, 2021). "In particular, the interferon gamma-induced chemokine CXCL10, also known as IP-10, reported to sustain tumour growth via autocrine loops and to drive T lymphocytes and NK cells through activation of CXCR3, is often upregulated in the same manner or simultaneously with CC inflammatory chemokines." (PMID 33801414, 2021). "This suggests that circulating IFN-γ-inducible chemokines may preferentially interact with CXCR3 expressed on tumor cells, while the action of CXCR3 on immune cells may be less prominent." (PMID 34501934, 2021). "CXCR3 mAb significantly prevented activated CD8α+ T cells from increasing in tumors, but not in lymph nodes, as a result of the anti-PD-L1 mAb treatment and significantly attenuated the tumor growth inhibition of the anti-PD-L1 mAb." (PMID 34230534, 2021). "Furthermore, it has been described that the lack of CXCR3 expression results in increased tumor growth and even lower levels of infiltrating T cells." (PMID 34321536, 2021). "However, several studies have demonstrated that the CXCR3 axis provokes tumour growth and metastasis, and more in-depth investigation is needed to elucidate the CXCL9-related mechanism." (PMID 34527583, 2021). "Thus, the authors evaluated the impact of neutralizing antibodies for IFNγ and CXCR3 on T-BsAb efficacy and showed that both antibodies were able to inhibit T cell recruitment into tumors and attenuate the inhibition of tumor growth by T-BsAb." (PMID 34832954, 2021). "The boosting effect of STING-L and cognate CART cells was more pronounced on endogenous tumor-specific T cells, as indicated by the increased number of tumor-infiltrating Tetr+ cells and their enhanced expression of CXCR3, CD25, and GzB in the combination group." (PMID 34810235, 2021). "CCR5-CCL5 axis was induced to enhance NK cell infiltration in tumor tissue, and CXCR3 on NK cells also could interact with CXCL9, CXCL10, and CXCL11 from tumor cells." (PMID 33918941, 2021). "Interestingly, paclitaxel-mediated inhibition of CXCR3+ T-cell recruitment to tumour tissue was temporary." (PMID 33513866, 2021).
tumor (continued). "Interestingly, when looking at all BRCA tumor samples for differential CXCR3 expression between races, Black BRCA patients show increased CXCR3 expression compared to white patients." (PMID 34440489, 2021). "Importantly, A. muciniphila was associated with enhanced infiltration of immune cells in tumor sites as CCR9+CXCR3+CD4+ T cells were migrated to the site of tumor, and CD4+ T cells to CD4+FoxP3+ T cells (Tregs) ratio was elevated." (PMID 33369247, 2021). "The expression of CXCR3 on malignant tumor cells has been correlated to increased tumor growth and spread, while CCR2 participates in tumor metastasis by promoting the trafficking of tumor associated macrophages into the TME with consequent angiogenesis." (PMID 34869014, 2021). "At this point, we do not exclude the possibility that following peripheral administration some of the injected CXCL10-Ig or CXCL9-Ig would enter the tumor site, and therefore may have an additional contribution to CXCR3+ cell recruitment to the TEM." (PMID 34944943, 2021). "In addition, the BRCA cohort had significantly different CXCR3 expression between the tumor and adjacent normal tissue, showing CXCR3 upregulation in the tumor." (PMID 34440489, 2021). "The increasing expression level of CXCR3 could accelerate the accumulation of tumor microenvironment (TEM) cells by helping TEM cells rapidly migrating into inflamed tissues." (PMID 33869044, 2021). "CXCR3 is the receptor for CXCL10, a member of the CXC chemokine family with pro-inflammatory and anti-angiogenic properties that has been associated with a variety of human diseases, including tumor development, metastasis, and dissemination." (PMID 32256215, 2020). "While patterns of CXCR2 in immune cells were not consistent with the patterns of immune cells induced by CXCL5, CXCR3 was highly expressed in T cells in the tumour microenvironment of PAAD tissue, which was in agreement with the induced patterns change of immune cells induced by CXCL9/10." (PMID 31913856, 2020). "Indeed, T‐bet can drive the expression of CXCR3 and has been shown to be important for the infiltration and anti‐tumour activity of cytotoxic CD8+ T cells." (PMID 31803974, 2020). "For T cell chemotaxis into the tumor, the CXCR3/CXCL9,10,11 axis seems crucial." (PMID 33679726, 2020). "Interestingly we found the CXCL9, -10,-11/CXCR3 (fold change 9.5, 8, 14 and 2.5 with p = 0.0005–0.0001) axis to be significantly upregulated in the tumor tissue, promoting cancer cell proliferation and metastasis (autocrine axis)." (PMID 31960110, 2020). "However, CXCR3 has also been ascribed an angiostatic effect that blocks tumor neovascularization and some of its platelet-derived ligands work as anti-tumor agents by inhibiting lymphangiogenesis." (PMID 32161595, 2020). "Very recently Andy Luster and his group showed that anti PD-1 efficacy is reduced in CXCR3KO mice, and suggested that the interaction between CXCL9, largely produced by CD103+ dendritic cells (DC) at the tumor site, and CXCR3 on CD8+ T cells enhances anti PD-1 efficacy." (PMID 32547545, 2020). "Here, we show that suppression of the CCL2/CCR2 and CXCL10/CXCR3 axes by celecoxib in the tumor and the tumor microenvironment might contribute to antitumor effects." (PMID 32943658, 2020). "In addition, CXCL9,−10,−11/CXCR3 network was confirmed to affect tumor resistance to checkpoint inhibitors by regulating immune cells activation." (PMID 32974144, 2020). "CXCR3 is known to have a key role in T‐cell trafficking to inflammatory sites and to tumours." (PMID 32820615, 2020). "Interestingly, CXCL9-11 were also upregulated in the tumor microenvironment, resulting in the promotion of GvL by increasing CXCR3 + T cell infiltration into the tumor." (PMID 32560120, 2020). "Although when CXCR3 is expressed by tumor cells its ligands may promote tumor growth, many studies demonstrated that these chemokines exert immuno-angiostatic activities on the TME." (PMID 32582148, 2020).
tumor (continued). "Similarly, intra-tumoral injection of AAV-IL-27 into established J558 tumors resulted in induction of CXCR3 spleen and tumor T cells." (PMID 32292786, 2020). "Importantly, sorted CXCR3+ 4T1 cells had increased tumor-initiating ability compared with CXCR3− cells when co-injected subcutaneously in limiting dilutions with lung fibroblasts, and resulting tumors were significantly larger." (PMID 32198421, 2020). "In addition, genetic deletion of protein kinase A (PKA) resulted in increased expression of CXCR3 in CAR-Ts, which was associated with improved targeting to the tumor site and tumor control." (PMID 32244520, 2020). "CXCR3 neutralization demonstrated only partial reversal of tumor control in ALK5ΔCD8 animals, so this may be one mechanism by which TGFβ is active in these models." (PMID 32273499, 2020). "Notably, we found that Th17 cells decreased CXCR3 expression levels on CD8+ T cells in PB, which was rescued by Stattic; CXCR3+CD8+ T cell infiltration in tumor tissues was consistent with these results." (PMID 32503584, 2020). "Thus, we theorized that CXCR3 expression on CD8+ T cells plays an important role in the degree of CD8+ T cell infiltration in tumor tissues of CRC patients." (PMID 32503584, 2020). "The overexpression of CXCR3 might decrease proportion of Th2 cells and IL-4 level, reducing M2 macrophage infiltration and increased the dendritic cell and tumor-infiltrating lymphocyte." (PMID 33585188, 2020). "In another study, CXCR3 expression on CD8+ T cells was found to be essential for an anti-PD-1-induced anti-tumor response through a mechanism of co-localization of the T cells with dendritic cells inside the tumor." (PMID 34458892, 2020). "Expression of CXCL9 in the tumour tissues of PAAD patients correlated with its CXCR3 expression and treatment of CXCL9 could significantly induce the expression of CXCR3 in CD8+ cytotoxic cells." (PMID 31913856, 2020). "Thus, it is expected that in different tumor systems, chemokines acting through CXCR3 would act alongside with ICB activities, as was suggested by several published reviews." (PMID 32582148, 2020). "In addition, intra-tumor induction of CXCL10 enhanced the infiltration of CXCR3+ cytotoxic T lymphocytes, thereby improving the antitumor effect of other therapies in some rodent solid tumor models." (PMID 32582551, 2020). "Importantly, T‐bet can promote the expression of CXCR3 and both T‐bet and Eomes have been shown to be important for the tumour infiltration and anti‐tumour activity of cytotoxic CD8+ T cells." (PMID 31803974, 2020). "For NK cells the role of CXCR3 for tumor infiltration is less straight forward." (PMID 33679726, 2020). "The observed synergy in tumor rejection extended to different tumor models, was accompanied by increased numbers of activated T cells expressing high levels of Gzma, Gzmb, Perforin, Cxcr3, and increased intratumoural levels of Cxcl9 and Cxcl10 compared to wild-type mice." (PMID 32641748, 2020). "Taken together, these findings indicate that decreased expression of CXCR3 on CD8+ T cells during tumor progression may play an important role in CD8+ T cell infiltration in patients with advanced-stage tumors." (PMID 32503584, 2020). "However, anti-CXCR3 interfered with the anti-tumor activity, with 83% of ALK5ΔCD8 mice treated with αCXCR3 antibody developing tumors." (PMID 32273499, 2020). "Finally, we found that co-culture of tumor-antigen P1A-specific P1CTL cells with IL-27 in vitro resulted in significant upregulation of CXCR3 in P1CTL cells, suggesting that IL-27 can directly induce CXCR3 in tumor-specific T cells." (PMID 32292786, 2020). "Rather than assisting NK-mediated immune surveillance against tumor formation and metastasis, some reports have indicated that CXCR3- and CXCR4-mediated attraction of NK cells may impede immune responses." (PMID 31647037, 2019).
tumor (continued). "In the context of hematological malignancy growing in BM, boosting CXCR3 function in the tumor site may be harmful to cancer immunotherapy." (PMID 31699153, 2019). "This conclusion was supported by the observation that loss of CXCR3 in blood cells resulted in increased tumor incidence in mouse colon, but no changes in tumor size." (PMID 31775909, 2019). "Notably, adoptively transferred CXCR3+ tumor-specific CD8+ T cells were capable of infiltrating metastatic tumors in the lungs." (PMID 30899263, 2019). "Our results represent a paradigm shift in how CXCR3 regulates anti-tumor effector cell function." (PMID 31699153, 2019). "CXCR3 has long been known to promote the migration, activation, and differentiation of some immune cells in tumor microenvironment and has been shown to play an important role in neoplastic diseases." (PMID 31240220, 2019). "We hypothesize that inhibition of CXCR3 function on NK cells will result in increased tumor clearance, due to higher NK cell bone marrow infiltration." (PMID 31699153, 2019). "NKG2D-specific CART cells could recruit and activate endogenous antigen-specific cytotoxic CD8+ cells and CD4+ Th cells in the tumor site in a CXCR3-dependent manner, leading to improved tumor eradication." (PMID 31835562, 2019). "Consequently, CXCR3 directly or indirectly involves in tumor progression by regulating tumor outgrowth, migration, invasion, angiogenesis and immunity." (PMID 31831069, 2019). "Proteolytic cleavage of the tumor-suppressive CXCR3 and CX3CR1 chemokines impairs their functions and, on top of this, in feedback loops, the chemokines may even lead to increased expression of the proteases targeting themselves." (PMID 31482487, 2019). "This is not linked to CXCR3 expression on tumor cells or immunosuppressive regulatory T or myeloid cells since CXCR3 blockade was effective only after activated NK cell transfer." (PMID 31699153, 2019). "Increasing the recruitment of CCR9+CXCR3+CD4+ T lymphocvtes into tumor beds." (PMID 32010123, 2019). "Thus, to optimize the immunotherapeutic effect of CXCR3 targeting, combination strategies will have to deal also with the inhibition of NK cell functions promoted by factors in the tumor microenvironment." (PMID 31699153, 2019). "Interestingly, CXCR3 and its ligands can also be responsible for tumor growth and metastasis in situations where the tumor cells express the CXCR3 receptor." (PMID 30320116, 2018). "Moreover, CXCR3 levels expressed on CD8+ T cells isolated from tumor-free WT and ADAM28 KO mice and stimulated ex-vivo with IL-2 and IL-7 were similar between both groups." (PMID 30647853, 2018). "This is exciting data on TS induction of differential CXCR3 expression and function on peripheral versus tumor sites that might affect cancer progression." (PMID 29707158, 2018). "Some studies have shown that IL-1β could induce upregulation of CXC chemokine receptor 3 (CXCR3) in T cells and tumor cells." (PMID 30359318, 2018). "This includes chemokine receptors known as CCR5 and CXCR3 as well as adhesion molecules Lymphocyte Function-associated Antigen (LFA-1) and Very Late Antigen (VLA)-1, which is important for rolling and firm adhesion to tumor vascular endothelium." (PMID 30126117, 2018). "Thus, CXCR3 can be beneficial for both reducing systemic inflammation as well as for anti-tumor responses." (PMID 29707158, 2018). "However, at tumor sites, inhibition of CXCR3 expression on Tregs limits the effectiveness of Teffs recruitment and suppression of size and number of colorectal tumors." (PMID 29707158, 2018). "Importantly, CXCR3 has been shown to be indispensable for CD8+ effector T cell trafficking across tumor vasculature due to its role in intravascular adhesion, even in the absence of its ligands." (PMID 30319622, 2018). "CXCR3 chemokines may have divergent effects on tumor cells in part dictated by the array of two functionally CXCR3 splicing variants; CXCR3A and CXCR3B." (PMID 29416784, 2018).